FTL (ferritin light chain)
Description:
Stores iron in a soluble, non-toxic, readily available form. Important for iron homeostasis. Iron is taken up in the ferrous form and deposited as ferric hydroxides after oxidation. Also plays a role in delivery of iron to cells. Mediates iron uptake in capsule cells of the developing kidney (By similarity). Delivery to lysosomes by the cargo receptor NCOA4 for autophagic degradation and release or iron.
Synonyms: MGC71996; NBIA3; FTL1; LFTD
Tractability: Small molecule: a structure with a bound ligand is known; it has a binding pocket of medium quality. Antibody: its Gene Ontology location is reachable by antibodies, with high confidence. PROTAC: ubiquitination databases record sites on it; its protein half-life has been measured.
Gene: Protein-coding gene on chromosome 19 (48,965,275 to 48,967,896, forward strand). Ensembl gene ENSG00000087086.
Subcellular location: Cytoplasmic vesicle, autophagosome; Cytoplasm; Autolysosome
Subcellular location (Human Protein Atlas): Cytosol
Pathways (Reactome):
Vesicle-mediated transport: Golgi Associated Vesicle Biogenesis; Scavenging by Class A Receptors
Immune System: Neutrophil degranulation
Transport of small molecules: Iron uptake and transport
Gene Ontology:
Molecular function: identical protein binding; iron ion binding; protein binding; ferric iron binding; ferrous iron binding
Biological process: autophagy; erythrocyte differentiation; intracellular iron ion homeostasis; iron ion transport
Cellular component: autolysosome; extracellular exosome; ferritin complex; membrane; azurophil granule lumen; cytoplasm; cytosol; extracellular region; autophagosome
Genetic constraint (gnomAD): Loss-of-function variants: 16 observed, 15.59 expected, observed/expected ratio (o/e) 1.03, 90% interval 0.69 to 1.55. The upper end of that interval is the gene's LOEUF score, 1.55, which puts it in group 6 of 6, group 1 being the genes least tolerant of losing a copy. Missense variants: 183 observed, 232.83 expected, observed/expected ratio (o/e) 0.79, 90% interval 0.7 to 0.89. Synonymous variants: 73 observed, 92.5 expected, observed/expected ratio (o/e) 0.79, 90% interval 0.65 to 0.96.
Gene-disease validity (ClinGen):
ClinGen rates the evidence that FTL causes each of these diseases.
hereditary hyperferritinemia with congenital cataracts (autosomal dominant): Definitive. Hereditary hyperferritinemia with congenital cataracts is characterized by the association of early onset (although generally absent at birth) cataract with persistently raised plasma ferritin concentrations in the absence of iron overload.
Homologues: Orthologues: guinea pig Ftl (86% identical), rat Ftl1 (84% identical), rat Ftl1l2 (84% identical), rat LOC120102993 (84% identical), rat Ftl1-ps14 (83% identical), mouse Ftl1 (82% identical), mouse Ftl1-ps1 (82% identical), pig FTL (81% identical), rat AABR07041778.1 (81% identical), rat AC115277.1 (81% identical), rat LOC100362384 (81% identical), rat Ftl1l7 (79% identical), and 6 more. Paralogues in human: FTH1 (57% identical), FTMT (54% identical), FTHL17 (49% identical).
Diseases named in the same sentence as FTL in open-access papers:
FTL is named in the same sentence as 128 diseases in open-access papers, as found by Europe PMC text mining. Sharing a sentence is not in itself a finding about the gene and the disease. The quoted sentences say what the papers report.
neuroferritinopathy (25 papers, 2010 to 2025). Neuroferritinopathy is a late-onset type of neurodegeneration with brain iron accumulation (NBIA) characterized by progressive chorea or dystonia and subtle cognitive deficits. "Ceruloplasmin mutations cause Wilson’s disease, while FTL mutations cause neuroferritinopathy, both of which are characterized by basal ganglia degeneration and severe movement disorders, including parkinsonism." (PMID 39164482, 2025). "Mutations in the FTL gene lead to neuroferritinopathy, an autosomal dominant neurodegenerative disease with significant brain iron accumulation." (PMID 40082954, 2025). "Iron chelation is a promising treatment for neuroferritinopathy, with a causative link between FTL mutation, iron accumulation, and neurodegeneration." (PMID 38561955, 2024). "Variants in exon 4 affecting the C-terminal residues of the FTL protein are associated with a neurological disorder also referred to as neuroferritinopathy." (PMID 35625641, 2022). "In neuroferritinopathy, the mutations in the FTL gene affect protein folding and stability, which increases the intracellular iron availability and sensitivity to oxidative stress and DNA damage." (PMID 33809527, 2021). "HF, also known as neuroferritinopathy, is an autosomal dominant, adult onset, degenerative disease caused by mutations in the ferritin light chain (FtL) gene." (PMID 33244127, 2020). "Mutations in the ferritin light chain (FTL) gene cause neuroferritinopathy, an AD inherited disease with adulthood onset." (PMID 33092153, 2020). "Mutations in exon 4 of FTL gene that alter the C-terminal sequence and the length of the protein have been reported to cause neuroferritinopathy." (PMID 30678075, 2019). "Mutations in the ferritin light chain (FTL) gene cause the neurodegenerative disease neuroferritinopathy or hereditary ferritinopathy (HF)." (PMID 27574973, 2016). "Mutations that affect the ferritin light chain (FTL) lead to the autosomal dominant disease neuroferritinopathy." (PMID 25870938, 2016). "Neuroferritinopathy or hereditary ferritinopathy (HF) is an autosomal dominant movement disorder caused by mutations in the ferritin light chain (FTL) gene on chromosome 19q13.3." (PMID 27574973, 2016). "Neuroferritinopathy is caused by 9 types of mutation in the FTL gene, the most common is the 460InsA, with more than 40 patients described." (PMID 25689865, 2015). "In contrast, DNA variations in L-ferritin gene (FTL) are more common, and nucleotide insertions that modify the C-terminal region cause movement disorders named neuroferritinopathies, that are inherited with dominant transmission." (PMID 25689865, 2015). "Nucleotide insertions in the last exon of the ferritin light chain cause a neurodegenerative disease known as Neuroferritinopathy, characterized by iron deposition in the brain, particularly in the cerebellum, basal ganglia and motor cortex." (PMID 25689865, 2015). "Two forms are linked to mutations in genes directly involved in iron metabolism: neuroferritinopathy, associated to mutations in the FTL gene and aceruloplasminemia, where the ceruloplasmin gene product is defective." (PMID 24847269, 2014). "The Neuroferritinopathy (OMIM, 606159, also labeled as hereditary ferritinopathies or NBIA3) is a rare monogenic autosomal-dominant progressive movement disorder caused by mutations in the gene encoding the L chain of ferritin (FtL)." (PMID 24847269, 2014). "Herein, we review one of these - hereditary ferritinopathy (HF) or neuroferritinopathy, which is an autosomal dominant, adult onset degenerative disease caused by mutations in the ferritin light chain (FTL) gene." (PMID 23908629, 2013). "Mutations in the FTL gene on chromosome 19q cause neuroferritinopathy (also called hereditary ferritinopathy)." (PMID 23814539, 2013).
neuroferritinopathy (continued). "Outside of the IRE, rare mutations in the coding region of FTL have been associated with either neuroferritinopathy or hyperglycosylated serum ferritin associated with benign hyperferritinemia in the absence of cataract." (PMID 23592921, 2013). "NBIA is also uncommonly associated with acoeruloplasminaemia due to mutations in the coeruloplasmin (CP) gene and neuroferritinopathy associated with mutations in the FTL (ferritin light polypeptide) gene." (PMID 22416811, 2013). "Hereditary ferritinopathy (HF) or neuroferritinopathy is an autosomal dominant, adult onset neurodegenerative disease caused by mutations in the ferritin light chain (FTL) gene." (PMID 23908629, 2013). "Two other genes also cause NBIA, acoeruloplasminaemia due to mutations in the (ceruloplasmin) CP gene and neuroferritinopathy, caused by mutations in the FTL (ferritin light polypeptide) gene." (PMID 20619503, 2012). "Nucleotide duplications in exon 4 of the ferritin light polypeptide (FTL) gene cause the autosomal dominant neurodegenerative disease neuroferritinopathy or hereditary ferritinopathy (HF)." (PMID 21067605, 2010). "The neurodegenerative disease neuroferritinopathy or HF is an autosomal dominant, adult onset disease caused by mutations in the FTL gene that lead to the production of FTL polypeptides with abnormal C-termini." (PMID 21067605, 2010). "Lower levels of L-ferritin in PD, as in FTL gene mutations in neuroferritinopathy, may reduce the ability of ferritin to store iron, resulting in the release of iron." (PMID 33809527, 2021). "FTL genetic variants associated with Hereditary Ferritinopathy (neuroferritinopathy)." (PMID 31920471, 2019). "Until now, only two genes coding for iron proteins have been identified as responsible of NBIA subtypes: the ceruloplasmin gene (CP) causing aceruloplasminemia and the L-ferritin gene (FTL) altered in neuroferritinopathy." (PMID 24847269, 2014). "Defects in the FTL gene lead to abnormally high levels of serum ferritin (hyperferritinemia) in HHCS and benign hyperferritinemia, while low levels (hypoferritinemia) are present in neuroferritinopathy and in autosomal dominant and recessive L-ferritin deficiency." (PMID 30678075, 2019).
glioblastoma (19 papers, 2010 to 2025). The most malignant astrocytic tumor (WHO grade IV). "Likewise, glioblastoma-associated LM and PC/PV CAMs exhibited hypoxia-responsive traits, with FTL and NRP1 (encoding CD304) upregulation." (PMID 38123840, 2024). "It has been shown that FTL expression was increased in glioblastoma and acute myeloid leukemia, and silencing FTL inhibits glioblastoma cell proliferation through the GADD45/JNK pathway." (PMID 41281761, 2025). "Hypoxia-inducible FTL (ferritin light chain), one of the hub ferroptosis regulators, functions as a new biomarker for the responsiveness to temozolomide in glioblastoma, as well as a prognostic marker." (PMID 37693905, 2023). "For example, glioblastoma and breast cancer cells exhibited nuclear expression of FTL and FTH, respectively." (PMID 33287315, 2020). "Ferritin light chain (Ft-L) is upregulated in glioblastoma tumors relative to low-grade gliomas and knockdown of Ft-L results in inhibition of glioma cell growth." (PMID 31366108, 2019). "Xenograft studies showed that shRNA-mediated FTH1 or FTL knockdown suppressed tumorigenesis of glioblastoma cells." (PMID 28793787, 2018). "FTL-positive microglia/macrophages were frequent in glioblastomas, and high FTL levels correlated with shorter survival in the whole cohort (p = 0.01) and in patients with anaplastic astrocytoma (p = 0.02)." (PMID 28837569, 2017). "FTL expression levels were significantly higher in the glioblastoma multiform group compared with levels in the low-grade glioma group (P = 0.04)." (PMID 26871431, 2016). "For FTL mRNA expression, the geometric mean in the low-grade glioma group was 0.4, whereas it was 2.3 in glioblastoma multiform group." (PMID 26871431, 2016). "FTL may also be involved in the development of tumors, such as the proliferation rate of HeLa cells and glioblastoma multiforme (GBM) cells and the drug resistance process of breast cancer." (PMID 35651950, 2022). "In HeLa cells and glioblastoma cells, the expression of FTL can promote the growth of cancer cells." (PMID 36536381, 2022). "Ferritin light chain (FTL), a key protein in iron metabolism, is associated with the survival of glioblastoma multiforme (GBM) patients; however, the molecular mechanisms underlying this association remain largely unclear." (PMID 26871431, 2016). "In conclusion, FTL transcription is controlled by the YAP-TFCP2-dependent transcription complex and regulates ferroptosis sensitivity in glioblastoma cells." (PMID 34765600, 2021). "Although both FTH and FTL are upregulated in head and neck cancers, only FTH predicted negative prognosis, whereas the opposite was found in glioblastoma." (PMID 33287315, 2020). "For example, siRNA-mediated FTH1 knockdown decreased the LD50 of carmustine from 100 to 40 μM in U-251 glioblastoma cells, and similar depletion of FTH1 and FTL by miR-200b lowered the IC50 of doxorubicin from 20 to <5 μM in MDA-MB-231 breast cancer cells." (PMID 28793787, 2018). "It was not until 2016 that a study found that FTL expression was increased in glioblastoma and acute myeloid leukemia, and silencing FTL could inhibit the proliferation of tumor cells." (PMID 41281761, 2025). "In murine primary cultured neurons, fibroblast, and glioblastoma cells, FTL expression was not affected by OGD/R as severe hypoxia and might be a reaction specific to human cerebral organoids." (PMID 34168538, 2021).
glioma (18 papers, 2016 to 2025). A benign or malignant brain and spinal cord tumor that arises from glial cells (astrocytes, oligodendrocytes, ependymal cells). "Patients from the CGGA325 and CGGA693 databases were classified into high-risk and low-risk groups and the survival curves revealed that a high expression of FTL was associated with poor prognosis in glioma patients." (PMID 37441589, 2023). "FTL expression was positively correlated with the levels of the immunoinhibitory factors associated with the glioma TME." (PMID 37441589, 2023). "Tumor FTL levels were associated with prognosis in patients with lower grade glioma (LGG), whereas FTH1 levels were associated with prognosis in patients with liver hepatocellular carcinoma, HNSC, LGG, and kidney renal papillary cell carcinoma." (PMID 33864445, 2021). "Moreover, the upregulation of FTL was positively associated with a high immunoinfiltration score, microenvironment, macrophages, and M2 macrophages in glioma." (PMID 37441589, 2023). "So it was reasonable to infer that the high expression of FTL in HGG might be caused by the ubiquitous hypoxic-microenvironment in glioma." (PMID 32677981, 2020). "In U87 and U251 glioma cells, FTL was shown to be upregulated by hypoxia, and hypoxia-induced FTL was a positive regulator of EMT." (PMID 39852175, 2025). "It was found that FTL expression was significantly increased in GBM patients compared to those with low-grade glioma." (PMID 39001407, 2024). "The finding is consistent with a report demonstrating a positive correlation between FtL and β-catenin in glioma cells." (PMID 36829936, 2023). "Our study supports targeting FTL in combination with immune-checkpoint blockade therapy, which is expected to establish efficient therapeutic options for FTL intervention in glioma immunotherapy." (PMID 37441589, 2023). "Inhibition of FTL in TAMs attenuated glioma angiogenesis, promoted the recruitment of T cells and sensitized glioma to anti-PD1 therapy." (PMID 37441589, 2023). "We found that FTL expression was significantly higher in IDH1/2 wildtype gliomas and 1p/19q non co-deletion." (PMID 37441589, 2023). "We further demonstrated that TAMs overexpressing FTL significantly promoted the proliferation, invasion and migration of glioma cells." (PMID 37441589, 2023). "Based on these results, FTL significantly promotes M2 macrophage polarization and tumor angiogenesis in glioma." (PMID 37441589, 2023). "Flow cytometry analysis was also performed to evaluate the effect of FTL on major immune cell populations in the glioma microenvironment in vivo." (PMID 37441589, 2023). "We concluded that FTL regulated glioma angiogenesis by inducing macrophage polarization to M2-like phenotype." (PMID 37441589, 2023). "The correlations between FTL and various immune infiltration cells were analyzed through ssGSEA; the results showed that FTL was positively correlated with immune infiltration score, microenvironment and macrophages in glioma." (PMID 37441589, 2023). "We therefore tentatively conclude that FTL inhibition facilitated the immune-supported microenvironment and enhanced glioma sensitivity to anti-PD1 therapy." (PMID 37441589, 2023). "For example, overexpression of ferritin inhibits ferroptosis in PC-12 cells via ferritinophagy, whereas ferroptosis occurs in glioma cells by upregulating FTL and FTH expression." (PMID 34707773, 2021). "We found knockdown FTL in glioma cells increased the phosphorylation of β-catenin, while forced FTL expression decreased the phosphorylation of β-catenin." (PMID 32677981, 2020). "In our study, we tried to investigate the relationship between hypoxia and FTL expression in glioma." (PMID 32677981, 2020). "First, we found that FTL expression was positively correlated with MGMT expression in glioma tissues in three public datasets (TCGA,CGGA and Rembrandt)." (PMID 32677981, 2020). "While FTL expression in gliomas and its relationship with tumor malignancy remained poorly understood." (PMID 32677981, 2020).